DYRK1B (dual specificity tyrosine phosphorylation regulated kinase 1B)
Description:
Dual-specificity kinase which possesses both serine/threonine and tyrosine kinase activities. Plays an essential role in ribosomal DNA (rDNA) double-strand break repair and rDNA copy number maintenance. During DNA damage, mediates transcription silencing in part via phosphorylating and enforcing DSB accumulation of the histone methyltransferase EHMT2. Enhances the transcriptional activity of TCF1/HNF1A and FOXO1. Inhibits epithelial cell migration. Mediates colon carcinoma cell survival in mitogen-poor environments. Inhibits the SHH and WNT1 pathways, thereby enhancing adipogenesis. In addition, promotes expression of the gluconeogenic enzyme glucose-6-phosphatase catalytic subunit 1 (G6PC1).
Synonyms: MIRK; AOMS3
Tractability: Small molecule: a structure with a bound ligand is known; a high-quality ligand is known; it belongs to a druggable protein family. PROTAC: ubiquitination databases record sites on it; a small molecule that binds it is known.
Target class: Kinase; CMGC protein kinase Dyrk1 subfamily; Enzyme; CMGC protein kinase group; CMGC protein kinase DYRK family; Protein Kinase
Chemical probes: AZ191 (high quality), MU1210 (high quality), PD134124
Gene: Protein-coding gene on chromosome 19 (39,825,350 to 39,834,201, reverse strand). Ensembl gene ENSG00000105204.
Subcellular location: Nucleus; Nucleus, nucleolus; Chromosome
Subcellular location (Human Protein Atlas): Nucleoplasm; Mitotic chromosome
Gene Ontology:
Molecular function: protein binding; protein kinase activity; transcription coactivator activity; ATP binding; protein serine kinase activity; protein serine/threonine/tyrosine kinase activity; protein tyrosine kinase activity
Biological process: adipose tissue development; positive regulation of DNA-templated transcription; protein phosphorylation
Cellular component: chromosome; nucleoplasm; nucleus; nucleolus
Genetic constraint (gnomAD): Loss-of-function variants: 20 observed, 53.06 expected, observed/expected ratio (o/e) 0.38, 90% interval 0.26 to 0.55. The upper end of that interval is the gene's LOEUF score, 0.55, which puts it in group 2 of 6, group 1 being the genes least tolerant of losing a copy. Missense variants: 731 observed, 826.18 expected, observed/expected ratio (o/e) 0.88, 90% interval 0.83 to 0.94. Synonymous variants: 409 observed, 358.25 expected, observed/expected ratio (o/e) 1.14, 90% interval 1.05 to 1.24.
Homologues: Orthologues: chimpanzee DYRK1B (100% identical), dog DYRK1B (99% identical), pig DYRK1B (99% identical), rat Dyrk1b (98% identical), mouse Dyrk1b (97% identical), guinea pig DYRK1B (95% identical), macaque DYRK1B (92% identical), rabbit DYRK1B (86% identical), tropical clawed frog dyrk1a.2 (71% identical), zebrafish dyrk1b (68% identical), Drosophila melanogaster mnb (59% identical), Caenorhabditis elegans mbk-1 (44% identical), and 2 more. Paralogues in human: DYRK1A (65% identical), HIPK2 (26% identical), HIPK1 (25% identical), HIPK3 (25% identical), DYRK2 (24% identical), DYRK4 (24% identical), DYRK3 (23% identical), CLK2 (22% identical), HIPK4 (21% identical), CLK1 (20% identical), CLK3 (20% identical), CLK4 (20% identical).
Diseases named in the same sentence as DYRK1B in open-access papers:
DYRK1B is named in the same sentence as 71 diseases in open-access papers, as found by Europe PMC text mining. Sharing a sentence is not in itself a finding about the gene and the disease. The quoted sentences say what the papers report.
ovarian carcinoma (17 papers, 2012 to 2026). A malignant neoplasm originating from the surface ovarian epithelium. "The Mirk/Dyrk1B-mediated cell survival in ovarian cancer cells is associated with FoxO subcellular localization." (PMID 22159921, 2012). "DYRK1B promotes proliferative quiescence and yet is overexpressed or amplified in many hyperproliferative malignancies including ovarian cancer and pancreatic cancer." (PMID 39863750, 2025). "The suppressive impact of DYRK1B on the cell cycle cannot only be observed in normal cells, but is also preserved in many cancer cell lines, such as those of ovarian cancer, non-small cell lung cancer, glioblastoma, and PDAC." (PMID 39863750, 2025). "DYRK1B has been identified as a promigratory kinase in an siRNA screen of the highly motile SKOV3 ovarian cancer cells, and it was shown to be required for the migration of triple-negative breast cancer cells (TNBC)." (PMID 39482615, 2024). "DYRK1B overexpression has been observed in pancreatic and ovarian cancer, and in osteosarcomas and rhabdomyosarcomas." (PMID 37568654, 2023). "Recent study reported that inhibition of DYRK1B resulted in the downregulation of Akt phosphorylation in human pancreatic and ovarian cancer cells." (PMID 33500384, 2021). "Treatment of the ovarian cancer cells overexpressing DYRK1B with RO5454948 (inhibitor of both DYRK1 kinases) resulted in cell cycle re-entry and apoptosis, whereas the normal ovarian epithelial cells remained viable." (PMID 29942794, 2018). "The Mirk/dyrk1B gene is commonly amplified or upregulated in ovarian cancers, and Mirk is an active kinase in these cancers." (PMID 25061503, 2014). "In this study, we first evaluated protein expression of Mirk/Dyrk1B in both ovarian cancer and NSCLC cell lines." (PMID 23311607, 2013). "Our study demonstrates that Mirk/Dyrk1B is overexpressed in a variety of ovarian cancer cells and clinical specimens." (PMID 22159921, 2012). "In this study, we have identified that Mirk/Dyrk1B is overexpressed in a wide spectrum of ovarian cancer cell lines and primary tumors in which it is located in the cytoplasm." (PMID 22159921, 2012). "DYRK1B seems to be particularly tightly interwoven with this pathway as several points of interaction exist: (i) DYRK1B overexpression promotes mTOR activation and combined inhibition of DYRK1B and mTOR has superior impact on pancreatic and ovarian cancer cell growth compared to single treatment." (PMID 39863750, 2025). "Moreover, the Dyrk1B gene was found to be amplified or upregulated in approximately 75% of ovarian cancers." (PMID 38675189, 2024). "Furthermore, this analysis confirmed previous reports that the DYRK1B genomic region (19q13.2) is amplified in several tumor types including ovarian cancer and pancreatic adenocarcinoma." (PMID 39482615, 2024). "Pharmacological inhibition of Dyrk1B with RO5454948 inhibitor in the ovarian cancer cell lines TOV21G, SKOV3, and OVCAR3 similarly resulted in a selective effect on G0-quiescent cancer cells by promoting cell cycle re-entry, increased apoptosis, ROS levels, and DNA damage." (PMID 38675189, 2024). "In support of this role inhibiting DYRK1B in ovarian cancer cells was found to initiate apoptosis and to sensitize cancer cells to cisplatin (DNA damaging agent), supporting the assumption that DYRK1B could act in a similar way in COAD." (PMID 35454940, 2022). "Pharmacological inhibition of DYRK1B could downregulated Akt phosphorylation at Ser473 and Thr308 in human pancreatic and ovarian cancer cells." (PMID 33500384, 2021). "Furthermore, we confirmed previous reports on the amplification of the DYRK1B genomic region (19q13.2) in ovarian cancer and PDAC." (PMID 32751160, 2020). "Thus, DYRK1B knockdown negatively affects different aspects of ovarian cancer cell malignancy, including viability, proliferative potential and migratory capacity." (PMID 32751160, 2020).
ovarian carcinoma (continued). "Notably, DYRK1B protein expression is detected in 75% of resected ovarian tumors and up to 10% of ovarian cancers have DYRK1B gene amplification." (PMID 29942794, 2018). "Using DYRK1B-amplified pancreatic and ovarian cancer cells, co-targeting both kinases resulted in a significantly reduced GLI1 level and in increased cell death induction which could help to design new cancer therapies in the future." (PMID 27903983, 2017). "This might be particularly true if these cells express high levels of DYRK1B, such as many pancreatic and ovarian cancer cells." (PMID 27903983, 2017). "In addition, our results in the study demonstrate that the widely expressed Mirk/Dyrk1B in both ovarian cancer and NSCLC cells largely correlates the activated ERK1/2." (PMID 23311607, 2013). "In this study, we also found Mirk/Dyrk1B could be up-regulated by serum depleted culture or U0126 treatment in both ovarian cancer and NSCLC cells." (PMID 23311607, 2013). "Interestingly, the depletion of DYRK1B drove pancreatic and ovarian cancer cells to apoptosis." (PMID 37568654, 2023). "Finally, there also appears to be cross-talk between DYRK1B and the mammalian target of rapamycin (mTOR) pathway, with DYRK1B expression upregulated upon mTOR inhibition and mTOR/AKT activation induced by DYRK1B within the Hh signaling pathway in pancreatic and ovarian cancer cells." (PMID 32751160, 2020). "Continuing from these mechanistic findings, we could furthermore demonstrate that a pharmacological therapy combining the targeted inhibition of DYRK1B with that of PI3K/mTOR/AKT has strong effects on Hh/GLI signaling and on cell growth of DYRK1B-amplified pancreatic and ovarian cancer cells." (PMID 27903983, 2017). "In this study, knockdown of Mirk/Dyrk1B by siRNA in either ovarian cancer cells or NSCLC cells led to up-regulated activation of c-Raf-MEK-ERK1/2 pathway, accompanied by increased growth rate and cells from G0/G1 into S of cell cycle which could be blocked by U0126 in a dose-dependent manner." (PMID 23311607, 2013). "Pharmacological inhibition of mTOR results in upregulation of DYRK1B abundance in PDAC and ovarian cancer cells." (PMID 39863750, 2025). "In breast and ovarian cancer cells, the phosphorylation of FOXO1 by DYRK1B resulted in decreasing transcriptional activity." (PMID 37120440, 2023). "The cross-talk between DYRK1B and the MAPK pathway was further explored in ovarian cancer and NSCLC cell lines, where DYRK1B knockdown increased c-RAF and ERK activation." (PMID 32751160, 2020). "Addressing this issue therapeutically, we show that a pharmacological approach combining a DYRK1B antagonist with an mTOR/AKT inhibitor results in strong GLI1 targeting and in pronounced cytotoxicity in human pancreatic and ovarian cancer cells." (PMID 27903983, 2017). "Thus Mirk/dyrk1B kinase may be a therapeutic target in ovarian cancer ascites." (PMID 25061503, 2014). "Therefore, Mirk/Dyrk1B may be a novel target for treatment of ovarian cancer." (PMID 22159921, 2012). "Additionally, DYRK1B was found to activate PI3K/AKT pathway in COAD, its role in activating this pathway was reported in pancreatic and ovarian cancer cells." (PMID 35454940, 2022). "Researchers have demonstrated that Minibrain-related kinase/dual specificity tyrosine phosphorylation-regulated kinase 1B (Mirk/DYRK1B) blocks cyclin D1 and CDK4 which further regulates the survival signals and cell cycle arrest in pancreatic and ovarian cancer cells." (PMID 29616190, 2018). "Although it has been reported that Mirk could be negatively regulated by MAPK/ERK in colon cancer, our study is the first to show the possible interaction between Mirk/Dyrk1B and MAPK/ERK signals or sequestering with each other in both ovarian cancer and NSCLC cells." (PMID 23311607, 2013).
metabolic syndrome (15 papers, 2015 to 2025). A cluster of metabolic risk factors for CARDIOVASCULAR DISEASES and TYPE 2 DIABETES MELLITUS. "Mutation in Dyrk1b has been reported to activate adipogenic transformation and hepatic gluconeogenesis, leading to metabolic syndrome." (PMID 40287828, 2025). "Recent studies have revealed that mutations in DYRK1B linked to metabolic syndrome impair the chaperone-mediated maturation of its kinase domain, thereby disrupting its regulatory role in metabolic pathways." (PMID 40799825, 2025). "For example, gain-of-function mutations in DYRK1B have been linked to familial forms of obesity and metabolic syndrome, highlighting the importance of DYRK1B in regulating metabolic pathways." (PMID 40799825, 2025). "DYRK1B is associated with a metabolic syndrome known as abdominal obesity-metabolic syndrome 3 (AOMS3), which is characterized by abdominal obesity, type-2 diabetes, hypertension, and heart diseases (OMIM #615812)." (PMID 37329217, 2023). "Our group recently discovered another mutation, R102C, in dual specificity tyrosine phosphorylation regulated kinase 1b (Dyrk1b), that is strongly linked with metabolic syndrome in the carriers." (PMID 37242206, 2023). "Mutations in Dyrk1b are associated with metabolic syndrome and nonalcoholic fatty liver disease in humans." (PMID 34855620, 2022). "We investigated pathogenic DYRK1B variants causative of abdominal obesity-metabolic syndrome 3 (AOMS3) in a group of patients originally diagnosed with type 2 diabetes." (PMID 34193236, 2021). "Two missense variants of the human DYRK1B gene were recently found to be associated with a familial form of metabolic syndrome." (PMID 29764512, 2018). "Two missense mutations in the DH box of human DYRK1B were recently identified as causative of a rare familiar form of metabolic syndrome." (PMID 29764512, 2018). "The recent discovery that rare heterozygous mutations of DYRK1B completely co-segregate with a familial form of metabolic syndrome raises the question how these mutations alter the properties of DYRK1B to give rise to this complex phenotype." (PMID 28743892, 2017). "Two missense mutations of the DYRK1B gene have recently been found to co-segregate with a rare autosomal-dominant form of metabolic syndrome." (PMID 28743892, 2017). "Two missense mutations of the DYRK1B gene, H90P and R102C, were recently found to co-segregate with a rare autosomal-dominant form of metabolic syndrome called AOMS3 (abdominal obesity-metabolic syndrome 3, OMIM entry #615812)." (PMID 28743892, 2017). "The dual-specificity tyrosine-phosphorylation-regulated kinase, DYRK1B, is expressed de novo during myogenesis, amplified or mutated in certain cancers and mutated in familial cases of metabolic syndrome." (PMID 26346493, 2016). "Mutations in DYRK1B have been reported in an inherited form of metabolic syndrome associated with early-onset coronary artery disease, obesity, hypertension and diabetes." (PMID 26346493, 2016). "Interestingly, a mutation in DYRK1B at arginine residue (R102) is associated with metabolic syndrome and cardiovascular disease." (PMID 40287828, 2025). "In addition, its involvement in PI3K signaling and the discovery of DYRK1B mutations in the metabolic syndrome are intriguing." (PMID 27903983, 2017). "In addition, mutations in DYRK1B have been found in familial cases of metabolic syndrome and include: gain-of-function mutations R102C and H90P; putative loss-of-function mutations, such as L28P, and apparently benign mutations, such as G352A and P578S." (PMID 26346493, 2016). "Similarly, gain-of-function mutations in DYRK1B were recently implicated in metabolic syndrome." (PMID 25998054, 2015). "We had previously reported rare mutations in dual-specificity tyrosine phosphorylation–regulated kinase 1B (DYRK1B) that segregated perfectly with the traits of metabolic syndrome (MetS) in several kindreds." (PMID 34855620, 2022).
metabolic syndrome (continued). "Dual-specificity tyrosine phosphorylation-regulated kinase 1B (DYRK1B), a member of the CMGC group of kinases, is linked to metabolic syndrome, though the underlying molecular mechanisms remain unclear." (PMID 40287828, 2025). "Additionally, inhibition of DYRK1B has been shown to reduce adipogenesis, indicating its potential as a therapeutic target for the treatment of obesity in individuals with metabolic syndrome." (PMID 40799825, 2025). "The identification of Dyrk1b as a disease gene for abdominal obesity–metabolic syndrome (OMIM AOMS3) provided an exceptional opportunity to explore the underlying disease mechanisms and for the discovery of drug targets for a disorder that has one of the fastest growing incidences." (PMID 34855620, 2022). "Although both kinases share substrates, the distinct clinical outcome of inactivating mutations indicates they are not functionally redundant, i.e., a disorder within the autism spectrum for DYRK1A and a metabolic syndrome for DYRK1B (abdominal obesity metabolic syndrome-3, OMIM#615812;)." (PMID 32751160, 2020). "On the other hand, emerging insights into DYRK1B promotion adipogenesis and involvement in metabolic syndrome suggest that DYRK1B may potentially relevant to fat cell malignancy." (PMID 29568347, 2018). "Finally, mutants of DYRK1B found in cancer or metabolic syndrome are either neutral with respect to kinase activity or exhibit significant decreases in kinase activity." (PMID 26346493, 2016). "Finally, we show that DYRK1B mutants that have recently been described in cancer and metabolic syndrome exhibit normal or reduced intrinsic kinase activity." (PMID 26346493, 2016). "Additionally, DYRK1B has emerged as a significant player in metabolic syndrome." (PMID 40799825, 2025). "In particular, recently studies suggest that DYRK1B expression is noticeably increased during adipogenesis in 3T3-L1 cells and is also involved in lipogenesis, regulation of gluconeogenic enzymes, glucose-6-phosphatase, weight gain, appetite, and metabolic syndrome." (PMID 40799825, 2025). "Finally, we show that mutations in DYRK1B that are found in cancer or metabolic syndrome either inhibit or are without effect on DYRK1B kinase activity." (PMID 26346493, 2016). "At least one of these, R102C in metabolic syndrome, is defined as a gain-of-function mutation but clearly exhibits reduced kinase activity, raising the possibility that some effects of DYRK1B may not be strictly dependent on kinase activity." (PMID 26346493, 2016). "Indeed, some of the effects of DYRK1B in metabolic syndrome were apparently independent of DYRK1B kinase activity." (PMID 26346493, 2016).